GAS5 (growth arrest specific 5)
Diseases named in the same sentence as GAS5 in open-access papers (continued):
Sharing a sentence is not in itself a finding about the gene and the disease.
tumor (continued). "Neutralization of IL-10 and VEGF-A reduced tumour proli feration caused by GAS5 knockdown." (PMID 28099146, 2017). "Furthermore, lower GAS5 expression levels were associated with larger tumor sizes, poor tumor differentiation, and advanced pathological stages." (PMID 25925741, 2015). "Low-tumour GAS5 expression was associated with a poor prognosis." (PMID 21407217, 2011). "Moreover, GAS5 expression was negatively associated with the tumor grades." (PMID 31956395, 2020). "In addition, lower GAS5 levels were marginally associated with more numerous tumor foci." (PMID 30289954, 2018). "Moreover, LET decreased expression was associated with tumor micrometastasis and encapsulation, whereas GAS5 downregulation was associated with markers of poor prognosis (tumor size, lymph node metastasis, and clinical stage) and emerged as an independent predictor of 5-year DFS." (PMID 26064090, 2015). "Long non-coding RNA (lncRNA) GAS5 acts as a tumor suppressor and is frequently downregulated in various cancers, as well as in AML." (PMID 41898152, 2026). "Nevertheless, GAS5 appears to be mostly downregulated, classifying it as a tumor suppressor in most tumors." (PMID 41489907, 2026). "In detail, LINC-PINT, by directly recruiting EZH2, affects in vivo tumor growth in a xenograft model; GAS5 inhibits cell apoptosis and oxidative stress by recruiting E2F4 that reduces EZH2 expression." (PMID 40282449, 2025). "Ectopic expression of GAS5-specific siRNA (si-GAS5) significantly suppressed tumor cell growth and proliferation in HCC cells with high GAS5 expression." (PMID 40451925, 2025). "Functional assays using GAS5 siRNA in HCC cell lines demonstrated that reducing GAS5 expression significantly inhibited tumor growth, proliferation, survival and metastasis." (PMID 40451925, 2025). "One example involves the regulation of gene expression by the lncRNA GAS5, an intergenic tumor-suppressor lncRNA located on chromosome 1." (PMID 39941838, 2025). "These interactions underscore the role of GAS5 as a versatile tumor suppressor across multiple cancer models." (PMID 39941145, 2025). "GAS5/miRNA axes play significant roles in modulating cellular proliferation, differentiation, and apoptosis, allowing them to have a pivotal tumor-suppressive role in cancer progression." (PMID 39941145, 2025). "The methylation levels of the GAS5 promoter in the primary tumor samples in all three types of cancer maintained a steady beta value within the hypomethylation range (<0.25), indicating significantly reduced methylation levels compared with normal tissues." (PMID 39958058, 2025). "In KIRC, GAS5 expression showed a statistically significant positive correlation with tumor purity (r = 0.141, p = 0.00236), indicating a weak positive association." (PMID 39958058, 2025). "GAS5’s broad impact on tumor suppression through miRNA regulation parallels MEG3’s function, though it targets different specific miRNAs, enhancing the collective miRNA regulatory spectrum in this cancer type." (PMID 40242248, 2025). "Tumor suppressive effect of GAS5 was evident as the higher expression of GAS5 led to in apoptosis in HHUA and JEC (EC cell lines)." (PMID 39912983, 2025). "One notable lncRNA, Growth Arrest-Specific 5 (GAS5), has been identified as a tumor suppressor in various cancers, including CRC." (PMID 40243746, 2025). "The correlations between GAS5 expression and immune cell infiltration across selected cancer types were analyzed to understand the tumor immune microenvironment." (PMID 39958058, 2025). "Long noncoding RNA growth arrest-specific transcript 5 (GAS5) has been identified as a tumor suppressor due to its downregulation in several cancers." (PMID 40451925, 2025). "Given its crucial role in the regulation of cellular proliferation and differentiation, GAS5 is deemed a novel tumor suppressor in various cancers." (PMID 39941145, 2025).
tumor (continued). "Among the prognostic biomarkers identified for LIHC and KIRC, such as bone marrow kinase (BMX), GAS5 distinguishes itself through its upregulation and context-dependent modulation of the tumor-immune microenvironment." (PMID 39958058, 2025). "Humanin and GAS5 emerged as candidate tumor suppressors, while exosomal miR-21 and miR-103 showed strong oncogenic profiles and marked discriminatory power." (PMID 40768089, 2025). "Traditionally viewed as a tumor suppressor, GAS5 inhibits angiogenesis, proliferation, invasion and migration in multiple malignancies and enhances sensitivity to radiotherapy and chemotherapy by promoting cell cycle arrest." (PMID 40451925, 2025). "GAS5 has been considered a tumor suppressor; it regulates the cell cycle by keeping cells at the G0/G1 phase, inhibits cell proliferation, and induces apoptosis; all these mechanisms contribute together to inhibit cancer development." (PMID 39958058, 2025). "A detailed analysis showed that the si-Gas5 + si-Smarca4 mix inhibited tumor growth more effectively than either si-Gas5 or si-Smarca4 alone." (PMID 40451925, 2025). "Inflammatory cytokines, such as IL-2, enhance the secretion of TNF-α and IFN-γ by NK cells but downregulate the tumor-suppressive lncRNA GAS5." (PMID 41229433, 2025). "Genetic variation analysis of GAS5 in various tumor types using data from TCGA and cBioPortal revealed alterations in 2% of cases (259 out of 10,967 samples from 32 studies), the most frequent type of alteration being amplifications." (PMID 39958058, 2025). "In order to obtain a general understanding of the differential expression of GAS5 between tumor and normal tissues, we employed the TIMER database to examine the expression level of GAS5 in 16 distinct cancer types." (PMID 39958058, 2025). "In vivo studies using the Ras-transgenic mouse model of HCC demonstrated that silencing GAS5 or SMARCA4 or overexpressing miR-423-3p significantly reduced tumor development." (PMID 40451925, 2025). "GAS5 is a long non-coding RNA (lncRNA) that functions as a tumor suppressor by regulating cell cycle progression and apoptosis." (PMID 41226688, 2025). "Previous reports identified GAS5 as a tumor suppressor lncRNA, typically downregulated in cancer cells." (PMID 40451925, 2025). "Encouragingly, individuals with high iNMDeff individuals with high RP9P and GAS5 in tumor samples from TCGA and healthy tissue samples from GTex." (PMID 41023738, 2025). "By acting as a ceRNA, GAS5 effectively derepresses either the expression of tumor suppressor genes or critical regulatory pathways that inhibit tumor proliferation, invasion, and resistance to therapy." (PMID 39941145, 2025). "The lncRNA GAS5, for instance, functions as a tumor suppressor and serves as a prognostic marker in OC." (PMID 39941838, 2025). "Conversely, tumor-suppressor lncRNAs, such as GAS5 and MEG3, can inhibit ERK activity, restoring apoptotic sensitivity." (PMID 41020820, 2025). "GAS5 is a very important lncRNA that functions as a tumour suppressor in several cancers including lung, breast, gastric, cervical, ovarian, renal, kidney, oesophagus and colorectal." (PMID 39912983, 2025). "Not only is GAS5 an effective tumor suppressor through its ability to regulate proliferation and differentiation, but GAS5 has also been demonstrated to inhibit cancer progression by driving cancer cells towards programmed cell death through autophagy." (PMID 39941145, 2025). "While GAS5 is recognized as a tumor suppressor in cancer, recent reports highlight its broader regulatory capacity in non-cancerous diseases." (PMID 39941145, 2025). "The GAS5 lncRNA is acknowledged to be a tumor-suppressor gene (TSG) that hinders glucocorticoid receptor signaling by sponging miR-21 and regulating translation." (PMID 40429961, 2025). "Growth arrest-specific transcript 5 (GAS5) is a long noncoding RNA (lncRNA) with potential as a tumor suppressor in a subset of cancers." (PMID 39958058, 2025).
tumor (continued). "In cancer, GAS5 consistently demonstrates its ability to function as a powerful tumor suppressor through many miRNAs, most notably through the well-characterized GAS5/miR-21 axis." (PMID 39941145, 2025). "GAS5, a well-established tumor suppressor lncRNA, induces apoptosis by sequestering the glucocorticoid receptor, thereby inhibiting its anti-apoptotic effects and increasing the sensitivity of cancer cells to apoptotic signals." (PMID 39895777, 2025). "GAS5, a tumor-suppressive lncRNA, enhances radiosensitivity by promoting DNA damage accumulation via precise regulation of the ATM/p38/MAPK pathway." (PMID 41229433, 2025). "Experiments within xenograft mice models have confirmed the crucial role of GAS5 as a tumor suppressor due to its ability to act as a competing endogenous (ceRNA) for miR-21, sponging the potent pro-cancer regulator." (PMID 39941145, 2025). "GAS5 also acts as a tumor suppressor in various cancers through functioning as a ceRNA for many miRNAs, which can exacerbate conditions by contributing to the acceleration of cancer." (PMID 39941145, 2025). "GAS5, a well-documented lncRNA with tumor-suppressive potential, is involved in key cellular processes such as apoptosis and proliferation." (PMID 40243746, 2025). "Long non-coding RNAs, such as GAS5, are particularly interesting due to their significant roles in carcinogenesis and modulating tumor microenvironment." (PMID 39920655, 2025). "Tumor growth was significantly inhibited in mice implanted with GAS5-overexpressing cells compared to that in mice implanted with control cells." (PMID 38762546, 2024). "The noncoding isoforms of GAS5 exert an anti-tumor effect by inhibiting tumor cell proliferation and metastasis while promoting apoptosis." (PMID 39553554, 2024). "GAS5, therefore, acts as a tumor suppressor by regulating various miRNAs, inhibiting epithelial–mesenchymal transition, activating signaling pathways, and inhibiting cell cycle progression and other pathways." (PMID 38212314, 2024). "Growth-arrest-specific 5 (GAS5) is a specific lncRNA that acts as a tumour suppressor in multiple cancer types." (PMID 38812041, 2024). "The results showed that GAS5 is decreased in cancer tissues, especially in tumors with a larger size, deeper invasiveness and higher tumor stage." (PMID 39337410, 2024). "A study indicates that GAS5 is significantly reduced in CRC tumor tissues and cells, and knocking down GAS5 can promote apoptosis in cancer cells." (PMID 39026978, 2024). "The expression level of GAS5 serves as a biomarker for cancer diagnosis and prognosis, mirroring the biological attributes of the tumor and patient clinical outcomes." (PMID 39286016, 2024). "Existing data suggest that m6A has prognostic value and affects immune cell infiltration in brain cancers, and a well-characterized lncRNA GAS5 has been shown to have an m6A-dependent role in tumor suppression in colorectal cancer (CRC)." (PMID 39198884, 2024). "This foremost study introduces the long non-coding RNA PARTICLE into the context of human GBM pathogenesis while substantiating the role of GAS5 as a tumor suppressor." (PMID 38258133, 2024). "Based on previous studies, some lncRNAs have been assigned as oncogenic (MALAT1, PCA3, HOTAIR, H19, PARTICLE, etc.)or as tumour suppressors (GAS5, MEG3, TERRA, etc.)." (PMID 38790894, 2024). "In the sphere of immunoregulation, GAS5 influences immune-related genes or miRNAs, thereby affecting immune cells like T cells and NK cells, which is crucial for modulating tumor immune evasion." (PMID 39286016, 2024). "One of such lncRNA genes, GAS5, encompassing 12 exons and generating two mature RNA transcripts 24, 45, has been proposed as a tumor-suppressor gene 27 and a key regulator of bone diseases." (PMID 39239549, 2024). "GAS5 engages with specific miRNAs, such as miR-196a-5p and miR-378a-5p, to influence the expression of genes related to the cell cycle, thereby impacting tumor cell proliferation." (PMID 39286016, 2024).
tumor (continued). "The lncRNA GAS5 is downregulated in multiple cancers and acts as a tumor suppressor, including gastric cancer, lung cancer, hepatocellular carcinoma, cervical cancer, prostate cancer, and glioma." (PMID 38782769, 2024). "For instance, it has been demonstrated that the GAS5 lncRNA controls cell longevity and development, exhibits tumor suppressor function in a variety of malignancies, and regains sensitivity to chemotherapy medications." (PMID 39257589, 2024). "The overexpression of the tumor suppressor lncRNA GAS5 inhibits GC development through percolating miR-106a-5p through the Akt/mTOR pathway." (PMID 39125625, 2024). "Within the tumor microenvironment, GAS5 exerts multifaceted roles: it curtails tumor cell proliferation and fosters apoptosis, mediated by interactions with miRNAs or modulation of genes governing the cell cycle and apoptosis." (PMID 39286016, 2024). "The inhibition of GAS5 in CC cells has been observed to enhance proliferation, migration, and invasion, further underscoring its potential as a tumor suppressor in the development of CC." (PMID 38434620, 2024). "Pre-Novel _3 is located within an intron of the lncRNA growth arrest-specific transcript 5 (Gas5) gene, a lncRNA tumour suppressor." (PMID 37059894, 2024). "GAS5 is a well-studied tumor-suppressing lncRNA that is often downregulated in various cancers, including gastric and colorectal cancers as well as breast and liver cancers." (PMID 39553554, 2024). "In OS tissues and cells GAS5 expression level was found significantly decreased in comparison to normal tissues and cells, as expected for a tumor suppressor gene." (PMID 38835012, 2024). "Herein, we discovered a tumor-suppressing role for tumor cell-derived GAS5 in regulating tumor microenvironment." (PMID 38762546, 2024). "Prior studies have documented the tumor suppressive role of GAS5 in HCC, including enhancing radiosensitivity, inhibiting invasion, and poor prognosis associated with its downregulation." (PMID 39609501, 2024). "We had reported that GAS5 expression was negatively correlated with worse clinical characteristics in NSCLC specimens previously, including tumor size and TNM stage, and we analyzed its association with immune cell infiltration in the current study." (PMID 38762546, 2024). "In vivo, GAS5 overexpression inhibited tumor growth by negatively regulating miR-106a-5p expression." (PMID 39125625, 2024). "In our study, lncRNA GAS5, a widely known tumour suppressor that participates in myocardial injury, was proved to be upregulated in BMSC-Exos in this study, which is coincident with previous claims." (PMID 38812041, 2024). "Inactivating hypermethylation of the GAS5 gene and the tumor-suppressive function of this lncRNA have been previously reported in gastric, cervical, and other tumors, as well as by us in EOC." (PMID 39519394, 2024). "The biological functions of the FTO/GAS5/IGF2BP2/QKI axis was assessed using the tumor xenograft assay." (PMID 38782769, 2024). "Growth arrest-specific transcript 5 (GAS5) exhibits tumor suppressor activity in various cancer types." (PMID 38434620, 2024). "Then we adopted transwell assay to evaluate the influence of tumor cell-derived GAS5 on immune cell recruitment." (PMID 38762546, 2024). "For instance, lncRNA SLC25A21-AS1, LIMT and GAS5 inhibit tumor growth in OC through diverse mechanisms and signaling pathways." (PMID 38725621, 2024). "Additionally, GAS5 is implicated in reversing chemotherapy resistance by modulating specific signaling pathways or miRNAs and plays a role in regulating metabolic processes within the tumor microenvironment, affecting the energy metabolism and biosynthesis of tumor cells." (PMID 39286016, 2024).
tumor (continued). "The IHC analyses indicated that overexpression of GAS5 inhibited tumor cell proliferation (Ki-67 staining) and facilitated macrophage infiltration (F4/80 staining)." (PMID 38762546, 2024). "LncRNA growth arrest-specific 5 (GAS5) is a tumor-suppressive lncRNA that has an essential role in the tumorigenesis of various cancers." (PMID 38226210, 2024). "Their findings showed a correlation between the levels of GAS5 in circulating exosomes and both tumour size and TNM stage (p < 0.05)." (PMID 39464709, 2024). "GAS5 (Growth arrest-specific transcript 5): Previous literature findings have reported a significant decrease in the expression of GAS5, which was further linked to advanced tumor progression." (PMID 39448589, 2024). "GAS5 is downregulated in tumor cells; however, its overexpression can inhibit tumor cell proliferation and migration by inactivating the mTOR pathway." (PMID 37371481, 2023). "SNHG2, which is also known as growth arrest-specific transcript 5 (GAS-5), is located at chromosome 1q25 and acts as a tumour suppressor in multiple cancers." (PMID 36831352, 2023). "In most tumor models, lnc-GAS5, mainly located in the cytoplasm, is demonstrated to translocate to mitochondria and suppress the TCA cycle by interacting with the MDH2 protein." (PMID 37770905, 2023). "Animal experiments also confirmed that the tumor size of the GAS5 overexpression group was smaller, while that of the GAS5 knockdown group was larger." (PMID 37692844, 2023). "An increase in oncogenic lnRNAs lowers the percentage of apoptotic cells, which is on the contrary, enhanced by the forced expression of tumor suppressor lncRNAs, such as GAS5 and TCL6." (PMID 37370817, 2023). "Growth arrest specific 5 (GAS5) is located on chromosome 1q25 with a length of 650 nucleotides and is regarded as a potent tumor suppressor whose expression is associated with various cancers." (PMID 40226409, 2023). "Different published works have determined the GAS5 levels in solid biopsies using qRT-PCR analysis and confirmed GAS5 downregulation in tumor tissues from BC patients." (PMID 37444428, 2023). "Recently, large amount researched demonstrated that GAS5 is diffusely expressed in multitudinous tumor tissues, and is related to chemotherapy resistance." (PMID 37993867, 2023). "Growth Arrest Specific 5 (GAS5) is a tumor suppressor and is downregulated in many cancer types including BC." (PMID 37888204, 2023). "The results showed that tumor growth was faster in mice that had been treated with 7721-sora-RBM38-OE + GAS5-KD cells." (PMID 37296859, 2023). "The expression levels of SNORD44 and GAS5 in tumor samples were lower than those in control samples, and the expression of SNORD44 was positively correlated with the expression of GAS5 in tumor samples." (PMID 37492704, 2023). "Exosomes containing high expression levels of GAS5 can inhibit cell proliferation and tube formation and promote the apoptosis of HUVECs, contributing to repressed angiogenesis and tumor metastasis." (PMID 37476194, 2023). "In vivo, cisplatin-resistant A549 cells stably overexpressing GAS5 yielded lower tumor volumes when injected into nude mice as compared to vector controls." (PMID 37370745, 2023). "In contrast, the lncRNA GAS5 (Growth Arrest-Specific 5) has been shown to be downregulated in cancer and acts as a tumor suppressor by inhibiting cell proliferation and promoting apoptosis." (PMID 37627188, 2023). "Compared with healthy controls, serum exosomal lncRNA GAS5 is significantly downregulated in NSCLC patients, and its low expression is associated with advanced TNM stage and larger tumor size of NSCLC patients." (PMID 37476194, 2023). "For example, growth arrest specific 5 (GAS5), a potent tumor inhibitor, interferes with AKT/mTOR signaling pathway by targeting microRNA mir-103." (PMID 37021836, 2023). "GAS5 lncRNA expression has been shown to be decreased in various cancer types, suggesting its putative tumor-suppressing role." (PMID 38139448, 2023).